PKDCC (protein kinase domain containing, cytoplasmic)
Description:
Secreted tyrosine-protein kinase that mediates phosphorylation of extracellular proteins and endogenous proteins in the secretory pathway, which is essential for patterning at organogenesis stages. Mediates phosphorylation of MMP1, MMP13, MMP14, MMP19 and ERP29. Probably plays a role in platelets: rapidly and quantitatively secreted from platelets in response to stimulation of platelet degranulation. May also have serine/threonine protein kinase activity. Required for longitudinal bone growth through regulation of chondrocyte differentiation. May be indirectly involved in protein transport from the Golgi apparatus to the plasma membrane (By similarity).
Synonyms: SGK493; VLK; RLSDF
Tractability: Antibody: UniProt places it where antibodies can reach, with high confidence; its Gene Ontology location is reachable by antibodies, with high confidence; UniProt predicts a signal peptide or a membrane-spanning region.
Gene: Protein-coding gene on chromosome 2 (42,048,021 to 42,058,525, forward strand). Ensembl gene ENSG00000162878.
Subcellular location: Secreted; Golgi apparatus
Gene Ontology:
Molecular function: non-membrane spanning protein tyrosine kinase activity; protein tyrosine kinase activity; protein kinase activity; ATP binding
Biological process: peptidyl-tyrosine phosphorylation; skeletal system development; embryonic digestive tract development; lung alveolus development; negative regulation of Golgi to plasma membrane protein transport; positive regulation of bone mineralization; positive regulation of chondrocyte differentiation; roof of mouth development
Cellular component: extracellular region; Golgi apparatus
Genetic constraint (gnomAD): Loss-of-function variants: 33 observed, 38.37 expected, observed/expected ratio (o/e) 0.86, 90% interval 0.65 to 1.15. The synonymous counts are far from expectation, so gnomAD's model fits this gene poorly and the ratio says little. Missense variants: 676 observed, 546.5 expected, observed/expected ratio (o/e) 1.24, 90% interval 1.16 to 1.32. Synonymous variants: 323 observed, 240.65 expected, observed/expected ratio (o/e) 1.34, 90% interval 1.23 to 1.47.
Homologues: Orthologues: macaque PKDCC (98% identical), pig PKDCC (95% identical), dog PKDCC (94% identical), mouse Pkdcc (93% identical), rat Pkdcc (93% identical), chimpanzee PKDCC (91% identical), guinea pig PKDCC (72% identical), rabbit PKDCC (71% identical), tropical clawed frog pkdcc.2 (62% identical), zebrafish pkdcca (59% identical). Paralogues in human: MAP3K7 (17% identical), MAP3K7CL (4% identical).
Diseases named in the same sentence as PKDCC in open-access papers:
PKDCC is named in the same sentence as 16 diseases in open-access papers, as found by Europe PMC text mining. Sharing a sentence is not in itself a finding about the gene and the disease. The quoted sentences say what the papers report.
cleft lip (1 paper, 2025). Congenital defect in the upper lip where the maxillary prominence fails to merge with the merged medial nasal prominences. "However, three SNPs showed some weak evidence of an effect on PRS in the opposite direction to their effect on cleft lip phenotypes: rs62390705 (FBN2, 5q23.3) (P = 0.05), rs126280 (UTP25, 1q32.2) (P = 0.002), and rs4952552 (PKDCC, 2q14.2) (P = 0.04)." (PMID 41075272, 2025).
osteoporosis (1 paper, 2025). A condition of reduced bone mass, with decreased cortical thickness and a decrease in the number and size of the trabeculae of cancellous bone (but normal chemical composition), resulting in increased fracture incidence. "A colocalization analysis across multiple datasets identified six candidate loci, including the successfully replicated PKDCC rs12996954 variant, which may help explain the shared genetic basis between osteoporosis and RCTs." (PMID 40866365, 2025).
pseudoachondroplasia (1 paper, 2023). Pseudoachondroplasia is characterized by severe growth deficiency and deformations such as bow legs and hyperlordosis. "In Family 4, an individual initially suspected to have pseudoachondroplasia had inherited a c.290_320del31, p.(Leu97Profs*123) variant in PKDCC from her unaffected mother alongside a second variant c.492delG, p.(Leu165Serfs*65)." (PMID 36896672, 2023).
Rhizomelia (1 paper, 2023). Disproportionate shortening of the proximal segment of limbs (i.e. the femur and humerus). "In Family 3, a homozygous c.606dupG, p.(Leu203Alafs*96) PKDCC variant was shared by two sisters with short stature, rhizomelia and bilateral clinodactyly." (PMID 36896672, 2023).
cancer (3 papers, 2016 to 2023). A tumor composed of atypical neoplastic, often pleomorphic cells that invade other tissues. "Phosphorylation of these proteins potentially controls the protein activities and impacts cell adhesion and migration, suggesting a possible functional interaction between PKDCC and cancer." (PMID 36825005, 2023). "The regulation of PKDCC expression and secretion is not yet understood, as well as its physiological function in human cancers, but its function in a variety of diseases has been explored." (PMID 36825005, 2023). "Genes coding for proteins supporting cancer cells survival or proliferation such as FOXD1 or EIF5A appeared up-regulated in resistant and not in sensitive, while E-cadherin, CLDN7, MDK, PKDCC, and JAG1 were more down-regulated." (PMID 27835869, 2016).
cardiovascular disease (1 paper, 2022). "The role of other genes such as NARS, PKDCC, ARHGDIG, STARD10, and MAPK12 expressed in the hypertrophy stage requires more investigation in cardiovascular disease." (PMID 35625658, 2022).
skeletal dysplasia (1 paper, 2023). Any Mendelian diseases that affects growth and development of the skeleton. "In 2019, biallelic variants in the human orthologue (PKDCC) were identified in patients with skeletal dysplasia." (PMID 36896672, 2023). "There was a 2 of 253 incidence of PKDCC positive cases amongst patients recruited to the 100 kGP (v15, 26 May 2022) due to unexplained skeletal dysplasia." (PMID 36896672, 2023).
PKDCC also shares sentences with these, for which no sentence is quoted: asthma (1 paper); atopic asthma (1); cholestasis (1); fibrosis (1); glaucoma (1); Hepatic steatosis (1); hepatocellular carcinoma (1); liver inflammation (1); steatosis (1).